FHOD1 (formin homology 2 domain containing 1)
Description:
Required for the assembly of F-actin structures, such as stress fibers. Depends on the Rho-ROCK cascade for its activity. Contributes to the coordination of microtubules with actin fibers and plays a role in cell elongation. Acts synergistically with ROCK1 to promote SRC-dependent non-apoptotic plasma membrane blebbing.
Synonyms: FHOS
Tractability: PROTAC: ubiquitination databases record sites on it; its protein half-life has been measured.
Gene: Protein-coding gene on chromosome 16 (67,229,387 to 67,247,539, reverse strand). Ensembl gene ENSG00000135723.
Subcellular location: Cytoplasm; Cytoplasm, cytoskeleton; Cell projection, bleb
Subcellular location (Human Protein Atlas): Cytosol
Gene Ontology:
Molecular function: identical protein binding; protein binding; actin filament binding
Biological process: positive regulation of stress fiber assembly; positive regulation of transcription by RNA polymerase II; regulation of stress fiber assembly; actin filament organization
Cellular component: cytosol; membrane; nucleus; stress fiber; cytoplasm; cytoskeleton; bleb; intercalated disc
Genetic constraint (gnomAD): Loss-of-function variants: 89 observed, 115.16 expected, observed/expected ratio (o/e) 0.77, 90% interval 0.65 to 0.92. The upper end of that interval is the gene's LOEUF score, 0.92, which puts it in group 3 of 6, group 1 being the genes least tolerant of losing a copy. Missense variants: 1,444 observed, 1,590.8 expected, observed/expected ratio (o/e) 0.91, 90% interval 0.87 to 0.95. Synonymous variants: 617 observed, 657.29 expected, observed/expected ratio (o/e) 0.94, 90% interval 0.88 to 1.
Homologues: Orthologues: chimpanzee FHOD1 (99% identical), macaque FHOD1 (92% identical), dog FHOD1 (90% identical), pig FHOD1 (89% identical), rabbit FHOD1 (89% identical), mouse Fhod1 (88% identical), rat Fhod1 (88% identical), guinea pig FHOD1 (87% identical), zebrafish fhod1 (52% identical), Caenorhabditis elegans fhod-1 (34% identical), Drosophila melanogaster Frl (15% identical), Caenorhabditis elegans daam-1 (14% identical), and 3 more. Paralogues in human: FHOD3 (50% identical), FMNL2 (16% identical), INF2 (15% identical), FMNL1 (15% identical), FMNL3 (15% identical), DAAM1 (15% identical), DIAPH3 (15% identical), DAAM2 (15% identical), DIAPH1 (15% identical), DIAPH2 (14% identical), FMN2 (12% identical), GRID2IP (12% identical), and 6 more.
Diseases named in the same sentence as FHOD1 in open-access papers:
FHOD1 is named in the same sentence as 24 diseases in open-access papers, as found by Europe PMC text mining. Sharing a sentence is not in itself a finding about the gene and the disease. The quoted sentences say what the papers report.
breast carcinoma (9 papers, 2012 to 2023). "The actin‐regulating formin protein FHOD1 was frequently overexpressed in several breast cancer cells." (PMID 37211949, 2023). "FHOD1 expression is upregulated in many cancers including glioma, melanoma, squamous cell, gastric, and breast cancers." (PMID 37215084, 2023). "Reducing the expression of FHOD1 in the breast cancer cells decreases the activity of SRF through reduced actin filament formation." (PMID 37215084, 2023). "In this recent study, FHOD1 was shown to promote mesenchymal phenotype and invasion of breast cancer cells." (PMID 24086398, 2013). "In line with this, FHOD1 silencing was shown to reduce migration and invasion of breast cancer cells by inhibiting the nuclear translocation of the SRF coactivator MRTF-A, which is sequestered in the cytoplasm by G-actin and regulated by changes in actin dynamics." (PMID 36927816, 2023). "In breast cancer cells, FHOD1 is a target of downregulation by miRNA-200c." (PMID 37215084, 2023). "Transient transfection of miR-200c reduced both formin homology domain-containing protein 1 (FHOD1) and Mg2+/Mn2+-dependent protein phosphatase 1F (PPM1F) levels, and inhibition of the miR-200b/c/429 cluster in MCF7 breast cancer cells increased FHOD1 and PPM1F levels." (PMID 25762624, 2015). "Examples of this function are DIAPH1-3 and DAAM1 in breast cancer, DIAPH1 in glioma, FMNL1 in nasopharyngeal carcinoma, FMNL2 in colorectal cancer, and FHOD1 in oral squamous carcinoma." (PMID 34685534, 2021). "For instance, miR-200 was shown to target cytoskeleton remodeling proteins in breast cancer cells, including WASF3, Moesin, FHOD1, PPM1F, WIPF1 and Cofilin2, functional mediators of miR-200 in the suppression of invasion and/or metastasis." (PMID 26334393, 2015).
glioma (4 papers, 2021 to 2025). A benign or malignant brain and spinal cord tumor that arises from glial cells (astrocytes, oligodendrocytes, ependymal cells). "Taken together, these results indicated that the high expression of FHOD1 was associated with poor outcomes in glioma patients." (PMID 37211949, 2023). "In addition, HSPB1 was overexpressed in FHOD1‐deficient T98G and U251 glioma cells." (PMID 37211949, 2023). "Heat map of the top 10 altered proteins indicated that FHOD1 was the most significantly upregulated protein, suggesting FHOD1 is a promising predictive biomarker for glioma." (PMID 37211949, 2023). "Silencing of FHOD1 remarkably promoted the ferroptosis sensitivity and growth inhibition in glioma cells through inhibiting heat‐shock protein B (HSPB1)." (PMID 37211949, 2023). "Colony formation assay indicated the inhibitory effect of FHOD1 depletion on the growth of glioma cells T98G and U251." (PMID 37211949, 2023). "Pancancer analysis revealed the up‐regulated FHOD1 in several cancers, including renal clear cell carcinoma, pancreatic adenocarcinoma, and glioma." (PMID 37211949, 2023). "In summary, our research mainly indicated FHOD1 as a promising negative regulator for ferroptosis in glioma." (PMID 37211949, 2023). "Recent research has indicated that FHOD1 overexpression in glioma attenuates ferroptosis by targeting HSPB1 signaling." (PMID 37723588, 2023). "In this study, we first studied the biological significance of FHOD1 in the regulation of ferroptosis in glioma cells." (PMID 37211949, 2023). "In three datasets from the CGGA database, mRNA_array_301, mRNAseq_325, and mRNAseq_693, the glioma patients with low FHOD1 expression displayed favorable overall survival (OS)." (PMID 37211949, 2023). "Depletion of FHOD1 inhibited the tumor volume and weight, indicating a tumor‐promoting role of FHOD1 in glioma." (PMID 37211949, 2023). "In this study, we explored the functional roles of FHOD1 signaling in the regulation of ferroptosis in glioma cells." (PMID 37211949, 2023). "Clarifying the understanding of molecular mechanisms and biological functions of FHOD1 in glioma biology would be of great significance to improve the prognosis and therapeutic response." (PMID 37211949, 2023). "Colony formation and CCK‐8 experiments both suggested that ectopic expression of HSPB1 obviously blocked the growth‐inhibitory effect of FHOD1 knockdown in glioma cells." (PMID 37211949, 2023). "The CCK‐8 assay indicated that FHOD1 knockdown significantly increased erastin‐induced inhibition of proliferation in glioma cells T98G and U251." (PMID 37211949, 2023). "In our study, FHOD1 was identified to be the most significantly upregulated protein in glioma tissues." (PMID 37211949, 2023). "Collectively, these findings suggested that FHOD1 protected glioma cells against ferroptosis via down‐regulating HSPB1 expression." (PMID 37211949, 2023). "Accordingly, we found that FHOD1 knockdown significantly increased elastin‐induced ferroptosis in glioma cells T98G and U251." (PMID 37211949, 2023). "We also explored the regulatory roles of abnormally expressed formin homology 2 domain‐containing protein 1 (FHOD1) in glioma ferroptosis sensitivity." (PMID 37211949, 2023). "We first used the short hairpin RNAs (shRNAs)‐mediated knockdown strategy to downregulate FHOD1 expression in glioma cells T98G and U251." (PMID 37211949, 2023). "Multiple glioma datasets revealed that the glioma patients with low FHOD1 expression displayed favorable survival time." (PMID 37211949, 2023). "Functional analysis proved that the knockdown of FHOD1 inhibited cell growth and improved the cellular sensitivity to ferroptosis in glioma cells T98G and U251." (PMID 37211949, 2023). "FHOD1 knockdown could enhance the ferroptosis sensitivity of glioma cells via up‐regulating the methylated heat‐shock protein B (HSPB1)." (PMID 37211949, 2023).
glioma (continued). "Moreover, overexpression of HSPB1 in FHOD1‐depleted glioma cells significantly reduced the inhibition of cell growth." (PMID 37211949, 2023). "Moreover, the expression levels of HSPB1 were found significantly reduced in FHOD1‐depleted glioma cells T98G and U251." (PMID 37211949, 2023). "The glioma patients with low FHOD1 expression displayed favorable survival time." (PMID 37211949, 2023). "All these findings suggested the depletion of FHOD1 could increase the ferroptosis sensitivity of glioma cells via inhibiting HSPB1 signaling." (PMID 37211949, 2023). "Our findings indicate that FHOD1 is upregulated in glioma cells." (PMID 37211949, 2023). "Two glioma cells T98G and U251 were utilized to evaluate the roles of FHOD1 on cell growth." (PMID 37211949, 2023). "We performed immunohistochemical staining of FHOD1 on a glioma tissue microarray." (PMID 37211949, 2023). "In addition to triple-negative breast cancer, FHOD1 expression has been observed to be significantly uppregulated in glioma cells, a change that correlated strongly with the degree of malignancy and aggressiveness of gliomas, as well as with the prognosis of patients." (PMID 40364836, 2025). "Then, we would like to explore whether aberrant FHOD1 mediates ferroptosis of glioma cells." (PMID 37211949, 2023). "Moreover, the pro‐ferroptotic effects of FHOD1 knockdown in glioma cells could be effectively impaired by HSPB1 overexpression in vitro and in vivo." (PMID 37211949, 2023). "Knockout of FHOD1 could enhance the ferroptosis sensitivity of glioma cells." (PMID 37211949, 2023). "Pearson correlation analysis indicated the positive correlation between FHOD1 expression and HSPB1 expression in both glioblastoma multiforme (GBM) and lower‐grade glioma (LGG) tissues." (PMID 37211949, 2023). "We first explored the expression correlation between FHOD1 and HSPB1 proteins in glioma cohorts from Xiangya Hospital, Central South University." (PMID 37211949, 2023). "In T98G and U251 glioma cells, HSPB1 overexpression suppressed the FHOD1 knockdown‐mediated upregulation of TRF1, a ferroptosis‐positive regulator." (PMID 37211949, 2023).
melanoma (4 papers, 2013 to 2025). A malignant, usually aggressive tumor composed of atypical, neoplastic melanocytes. "The actin-associated formin homology 2 domain containing protein 1 (FHOD1) gene is upregulated in melanomas and modifies proliferation and tumor growth, and the HSD11B2 plays a role in metastasis in colorectal cancer." (PMID 34178034, 2021). "In melanoma cells, overexpression of FHOD1 has been found to cause an elongated phenotype and increased migration." (PMID 24086398, 2013). "Furthermore, FHOD1’s overexpression in glioblastoma and melanoma underscores its role in promoting tumor invasion and metastasis, marking it as a potential target for therapeutic interventions and a marker of advanced disease stages in cancers like gastric cancer." (PMID 41262249, 2025).
colorectal cancer (3 papers, 2021 to 2025). A primary or metastatic malignant neoplasm that affects the colon or rectum. "In colorectal cancer cells, stimulation of CD21 triggers the generation of mechanical forces by Rho GTPase and Rac1, which recruit FHOD1 to the vicinity of CD21." (PMID 40364836, 2025).
gastric cancer (3 papers, 2021 to 2025). A primary or metastatic malignant neoplasm involving the stomach. "To study the localization and expression pattern of these formins in gastric cancer cells, we performed double immunofluorescence staining of F-actin and FHOD1 or FMNL1 in MKN28, AGS and MKN45 cells (respectively)." (PMID 34115237, 2021). "Our study is the first one to characterize these formins in intestinal gastric cancer tissue samples and investigate the correlation between cancer cell-specific FHOD1 and FMNL1 protein expression and intratumoral T lymphocyte infiltration." (PMID 34115237, 2021). "An interesting research revealed that formin homology 2 domain containing 1 (FHOD1) and formin‐like 1 (FMNL1), family members of Formin, are correlated with tumor‐infiltrating lymphocytes in gastric cancer, which first linked Formin proteins with anti‐tumor immunity." (PMID 36311172, 2022). "To assess the prognostic significance of FHOD1 and FMNL1 expression in intestinal gastric cancer, we used the KM-plotter database for Kaplan–Meier survival analyses." (PMID 34115237, 2021). "To characterize FHOD1 and FMNL1 expression in gastric cancer cell lines and validate antibodies for tissue stainings, we studied FHOD1 and FMNL1 protein expression in three publicly available cell lines; MKN28, AGS and MKN45." (PMID 34115237, 2021). "We further characterized FHOD1 and FMNL1 protein expression levels and patterns in gastric cancer cells." (PMID 34115237, 2021). "In addition, we characterized FHOD1 and FMNL1 expression in cultured gastric cancer cells." (PMID 34115237, 2021).
glioblastoma (3 papers, 2020 to 2025). The most malignant astrocytic tumor (WHO grade IV). "After dichotomization, 18 glioblastomas showed high expression of FHOD1 (score 2 or 3) and 69 low expression (score 0 or 1)." (PMID 32727404, 2020). "Previous studies that have focused on other formins than INF2 and FHOD1 have also indicated that individual formins participate in glioblastoma cell migration/invasion." (PMID 32727404, 2020). "In these samples, five glioblastomas were found to have diffusely infiltrating cells expressing moderate/high FHOD1 and/or INF2 in more than 20% of tumour cells, while the solid tumour showed absent/low expression." (PMID 32727404, 2020). "Using a knockdown approach, we could for the first time show that the expression of INF2 and FHOD1 is necessary for efficient migration of glioblastoma cells." (PMID 32727404, 2020). "In 93 samples of IDH-wildtype glioblastomas, FHOD1 and INF2 expression (scores 1–3) could be detected in 84 and 46% of cases, respectively." (PMID 32727404, 2020). "Using immunohistochemistry, we studied the expression of two formins, FHOD1 and INF2, in tissue samples from 93 IDH-wildtype glioblastomas." (PMID 32727404, 2020). "Using immunohistochemistry, we demonstrated expression of formin proteins FHOD1 and INF2 in glioblastoma tissues." (PMID 32727404, 2020). "Using immunohistochemistry, we discovered that formins FHOD1 and INF2 are frequently expressed in glioblastoma tissue." (PMID 32727404, 2020). "To establish whether the most interesting formins from the transcriptomics analysis, FHOD1 and INF2, are expressed as protein in human glioblastoma, we performed immunohistochemistry on human glioblastoma samples." (PMID 32727404, 2020). "Therefore, the moderate/high expression of FHOD1 and INF2 in a subset of glioblastomas can be considered as overexpression." (PMID 32727404, 2020). "Formins FHOD1 and INF2 participate in glioblastoma cell migration." (PMID 32727404, 2020). "To evaluate whether FHOD1 or INF2 expression is altered in areas of diffuse infiltration as compared to solid tumour areas, we studied 10 representative glioblastoma samples as whole slides." (PMID 32727404, 2020).
atherosclerosis (1 paper, 2025). A disease characterized by the build-up of fatty material and calcium deposition in the arterial wall resulting in partial or complete occlusion of the arterial lumen. "By identifying and validating the association of hub genes, such as FHOD1 and IRF7, with SMC-derived macrophages, we provide a new conceptual framework that parallels oncogenic processes in atherosclerosis." (PMID 41262249, 2025). "To further investigate the role of IRF7 and FHOD1 in atherosclerosis, we measured their expression in both human and mouse atherosclerotic tissues." (PMID 41262249, 2025). "Understanding how these genes regulate SMC-to-MAC transitions may reveal new mechanisms of SMC plasticity and vascular inflammation, highlighting FHOD1 and IRF7 as potential therapeutic targets to mitigate vascular remodeling and atherosclerosis progression." (PMID 41262249, 2025).
dilated cardiomyopathy (1 paper, 2020). Cardiomyopathy which is characterized by dilation and contractile dysfunction of the left and right ventricles. "Whether the elevated levels of FHOD1 at the intercalated disc are responsible for the increased levels of F-actin observed at this specialised site in dilated cardiomyopathy remains to be established." (PMID 32661904, 2020). "In cardiomyocytes, FHOD1 was found at the intercalated disc and costameres with expression levels being elevated in the hearts of mouse models of dilated cardiomyopathy and patients with the disease." (PMID 32661904, 2020).
head and neck cancer (1 paper, 2017). A primary or metastatic malignant neoplasm affecting the head and neck. "To further investigate this possibility, we investigated FHOD1 expression in two settings: head and neck cancer and thyroid cancer and thyroid cancer." (PMID 28815022, 2017). "Alternatively, this pattern might suggest that a shift in HRAS binding preference from FHOD1 to another partner such as RALGDS is favorable for head and neck cancer but less favorable for thyroid cancer." (PMID 28815022, 2017). "We observed that expression of FHOD1 is generally higher in thyroid tumors than in head and neck cancers, suggesting that Q61 may be more advantageous in thyroid cancer in part because of tumor type specific FHOD1 activity." (PMID 28815022, 2017).
prostate carcinoma (1 paper, 2019). A carcinoma that arises from epithelial cells of the prostate gland. "Maybe most interestingly in regard to our data on promotion of prostate cancer cell motility by PIM1 and NFATC1, there were several genes encoding regulators of the cytoskeletal actin network (INF2, FHOD1, ACTN3, CORO1B) and cell adhesion (COL6A2, PXN, ITGA5)." (PMID 31730483, 2019).
squamous cell carcinoma (1 paper, 2013). A carcinoma arising from squamous epithelial cells. "Here, we show that the formin family member FHOD1 is upregulated in squamous cell cancer EMT and influences the morphologic and functional hallmarks of EMT: actin organisation, cell migration and ability to degrade the extracellular matrix." (PMID 24086398, 2013).
Thrombocytopenia (1 paper, 2021). A reduction in the number of circulating thrombocytes. "The evidence presented here suggests that mDia1 is the major player in this phenotype, as mDia1 KOs show a tendency toward thrombocytopenia, which is exacerbated by the loss of Fhod1 in the DKOs." (PMID 32981398, 2021).
triple-negative breast carcinoma (1 paper, 2025). An invasive breast carcinoma which is negative for expression of estrogen receptor (ER), progesterone receptor (PR), and human epidermal growth factor receptor 2 (HER2). "For example, FHOD1 is frequently overexpressed in triple-negative breast cancer, specifically, overexpression of FHOD1 may promote malignant proliferation and metastasis of cancer cells by regulating cytoskeletal stability, cell migration ability, and modulation of various signaling pathways." (PMID 40364836, 2025).
viral infection (1 paper, 2013). "Remarkably, the cytoplasmic domain of human complement receptor 2 (CD21) binds to the FHOS/FHOD1 formin and facilitates its localization to the plasmalemma upon viral infection, demonstrating that interactions with membrane proteins can indeed recruit formins to membranes." (PMID 24204371, 2013).